STK11 (serine/threonine kinase 11)
Diseases named in the same sentence as STK11 in open-access papers (continued):
Sharing a sentence is not in itself a finding about the gene and the disease.
tumor (continued). "STK11 affects tumor cell growth through various important cellular pathways, and gene mutations can affect pathways such as AMPK, STING, and vascular endothelial growth factor, leading to immune suppression and changes in the metabolic environment, which resulted in tumor growth." (PMID 38736875, 2024). "An STK11 mutation reduces thecapacity of tumor cells to spark off AMP kinase, resulting in a higher power strain.Moreover, STK11 has an unfavorable impact on the mTOR cascade, which may result in aberrant mTOR signaling." (PMID 40230896, 2024). "The STK11 gene, as one of the most important tumor suppressors in NSCLC, its functional deficiency may be a key factor in regulating the tumor immune microenvironment." (PMID 38736875, 2024). "In addition, enzymes and signaling pathways related to amino acid metabolism can also affect tumor proliferation, for example, liver kinase B1 (LKB1), also known as serine-threonine kinase 11 (STK11), is inhibited when combined with asparagine." (PMID 38264667, 2023). "Additionally, some DGC patients tested negative for CDH1/CTNNA1 gene but had pathogenic variants in related tumor susceptibility genes, such as BRCA2, ATM, SDHB, PRSS1, MSR1, STK11, and PALB2." (PMID 37393258, 2023). "Our results also suggested that, by downregulating CD1E, STK11 deficiency may inhibit the differentiation of M1 macrophages in LUAD and then promote tumor growth." (PMID 37506141, 2023). "There were too few patients with an STK11/LKB1-variant tumor without weight loss (n = 2) to do regression analysis with this cohort." (PMID 37092555, 2023). "None of the patients that had tumor tissue available for sequencing had STK11 mutations suggesting loss of liver kinase B1." (PMID 37507657, 2023). "Similarly, higher LUAD cell viability and increased tumor size were also found in STK11‐mutant cells and mouse models." (PMID 37506141, 2023). "STK11/LKB1 mutations are detected in 10–20% of NSCLC and could result in a “cold” tumor with poor responses to ICIs." (PMID 37108738, 2023). "Thus, it was of interest that our recent discovery demonstrated that STK11 mutant NSCLCs treated with AXL inhibitors (targeting AXL in the tumor microenvironment dendritic cells) can now respond to immune checkpoint blockade therapy." (PMID 37035141, 2023). "Tumor intrinsic pathways including STK11/LKB1 and KEAP1 are associated with non-T cell-inflamed tumor microenvironment (TME), which is also called a “cold” tumor, thus impairing the clinical efficacy of immunotherapy." (PMID 37265800, 2023). "Supporting this observation of promoting a “cold tumor” microenvironment, several studies have demonstrated that STK11 mutations are associated with a low or no PD-L1 expression and an accumulation of immunosuppressive cells and cytokines (i.e., IL-6)." (PMID 37373999, 2023). "STK11/LKB1 loss directly promotes the formation of non-T-cell-inflamed tumor immune microenvironment in immune competent murine models of KRAS-mutant LUAD." (PMID 37261523, 2023).
tumor (continued). "Overall, this variant analysis of the tumor lines from our NSCLC cachexia screen suggested that non-synonymous variants in STK11/LKB1 are a potential predictive oncogenotype for CC." (PMID 37092555, 2023). "It has been reported that STK11 regulates cell polarity and functions as a tumour suppressor." (PMID 36380727, 2022). "STK11 is also under-expressed in C2 tumours compared with C1 tumours." (PMID 36207323, 2022). "Although inactivation of Rbm10, Rb1, or Apc did have similar effects on EGFR and KRAS mutant tumor growth, Serine/threonine kinase 11 (Stk11, also known as Lkb1) and SET domain containing 2, histone lysine methyltransferase (Setd2) inactivation had opposite effects in the two oncogenic settings." (PMID 35252550, 2022). "On a biological level, cancers with KRAS G12C and STK11 co-mutations treated with adagrasib were associated with increased tumour infiltrating lymphocytes, suggesting that the drug alters the tumour microenvironment and reverses STK11-induced immunosuppression." (PMID 36284306, 2022). "Liver kinase B1 (Lkb1, gene name Stk11) functions as a tumor suppressor in cancer." (PMID 36096803, 2022). "Furthermore, STK11/LKB1 and KEAP1 mutations are associated with an inert tumor immune microenvironment, with a reduced density of infiltrating cytotoxic CD8+ T cells and a neutrophil-enriched TME." (PMID 35407463, 2022). "At this moment, plasma circulating tumour DNA test revealed a STK11 mutation, which was not present at diagnosis." (PMID 35621690, 2022). "STK11 mutation was associated with a specific “cold” tumor immune microenvironment (TIME), characterized by production of pro-inflammatory cytokines, decrease in tumor-infiltrating CD8+ lymphocytes and low PD-L1 expression on tumor cells." (PMID 35281267, 2022). "Tumor cells with an abnormal STK11/LKB1 signaling axis were more likely to be surrounded by a “cold” immunosuppressive microenvironment characterized by the lack of inflammatory immune cells and the presence of multiple immunosuppressive cells (T-regulatory cells and tumor-associated neutrophils)." (PMID 35165542, 2022). "STK11 is a tumor suppressor that acts as an early gatekeeper." (PMID 36550395, 2022).
tumor (continued). "Despite the persistence of this positive predictive biomarker along with MSI, and the lack of aberrations in resistance genes (Janus kinase 2 [JAK2], phosphatase and tensin homolog [PTEN], serine/threonine kinase 11 [STK11]), the patient ended up with tumor progression on immunotherapy." (PMID 33608032, 2021). "Analysis of clinically relevant mutations revealed an epidermal growth factor receptor (EGFR) mutation for the donor of LCSCs_a as well as tumor tissue of the donor of LCSCs_c showed mutations in the genes for the KRAS proto-oncogene (KRAS) and serine/threonine kinase 11 (STK11)." (PMID 33800955, 2021). "Targeting of Stk11/Lkb1 significantly upregulated tumor burden and tumor cell proliferation." (PMID 33738287, 2021). "In addition, KRAS mutations can co-exist with other mutations in significant genes in cancer (e.g., STK11 and KEAP1) which induces tumor heterogeneity and promotes different responses to therapies." (PMID 35096591, 2021). "Interestingly, STK11 is also tumor suppressor that mediates tumor suppression via p21-induced senescence." (PMID 33513090, 2021). "Although the mutations of BRD4 and STK11 were associated with tumor stage in this study, the low frequency of BRD4 and STK11 mutations suggests that the sample population may be too small to cause false positive." (PMID 33432021, 2021). "While tumor samples with STK11 mutations were enriched for negative PD-L1 staining, tumor samples with high PD-L1 expression over 50% were less frequently mutated for STK11 or KEAP1." (PMID 34831355, 2021). "Additionally, clinical experiments have found that tumor mutation burden, immune cell infiltration, FGA, and STK11 mutations are all factors that influence the prognosis of immunotherapy." (PMID 32508023, 2020). "Our observations suggest that loss of STK11 and/or LKB1Y49D and LKB1D194Y somatic mutations in tumor cells could also contribute to angiogenesis and immune response through upregulation of cytokines." (PMID 32647375, 2020). "LKB1 (encoded by serine/threonine kinase 11, STK11) is a multifaceted enzyme that plays a tumor suppressive role by phosphorylating multiple substrates (e.g., AMPK and PTEN) to regulate crucial cellular processes including cell metabolism, polarity, differentiation, and proliferation." (PMID 32630372, 2020). "Besides, STK11/LKB1 is one of the most commonly inactivated tumour suppressors in NSCLC, especially in those harbouring KRAS mutations." (PMID 33116132, 2020). "Somatic Stk11 mutations are related with a number of human cancers; however, tissue-specific removal of Stk11 in mice does not necessarily lead to tumor formation (Ollila and Mäkelä, 2011)." (PMID 33236987, 2020). "STK11, known as liver kinase B1 (LKB1), regulates cell polarity and regarded as tumor suppressor." (PMID 32206449, 2020). "Then, we searched for a mechanism that could explain the decrease in the levels of STK11 expression in tumor biopsies." (PMID 32911741, 2020). "Tumor-cell-intrinsic oncogenic pathways including STK11/LKB1 and KEAP1 are associated with a “cold”, non-T cell-inflamed TME, thus significantly impairing clinical responses to ICI treatment." (PMID 33272262, 2020). "In a phase 3 trial conducted by Shu and colleagues, PD-L1 expression did not appear to be predictive of a treatment benefit, and patients with STK11 tumour mutations did not have significant radiographic or pathological responses." (PMID 33233705, 2020). "Additionally, STK11 is downregulated in tumor cells, and this behavior is thought to be part of the tumorigenesis processes and the higher rate of cell proliferation." (PMID 32911741, 2020). "STK11 silencing inhibited autophagy induction and tumor inhibition." (PMID 32419983, 2020).
tumor (continued). "STK11 mutations have been associated with low PDL1 expression on tumor cells in AD and with lack of response to immune checkpoint inhibitors." (PMID 30854794, 2019). "STK11 inactivation leads to the an increased infiltrate of protumoral neutrophils, a decrease of tumor-infiltrating cells and reduced PD1 and PD-L1 expressions in the tumor microenvironment, both in a KRAS-driven mouse model of lung adenocarcinoma and in cell lines." (PMID 31172347, 2019). "Indeed, the trans-differentiation from LAC to SqCC has been described both in humans and in mouse models, often when tumor cells are characterized by inactivation of the tumor suppressor gene LKB1/STK11, which occurs in up to 20% of LACs." (PMID 31266248, 2019). "The interaction of STK11 with CDK4 leads to the hypothesis that the tumour suppressor function of STK11 may be in part mediated by engaging the cell cycle regulatory machinery through its direct interaction with and inhibition of CDK4 activity." (PMID 28205554, 2017). "One of the causes of PJS was shown as a loss-of-function mutation in the human LKB1 gene, which is also known as serine–threonine protein kinase 11 (STK11), suggesting that LKB1 protein acts as a tumor suppressor." (PMID 22892070, 2012). "It will be interesting to determine whether LKB1 plays a similar role in epithelial stem cell biology, and whether spindle misorientation contributes to tumor formation in STK11 mutant epithelial tissues." (PMID 22815934, 2012). "AMP allosterically activates AMPK and facilitates phosphorylation of its catalytic subunit on residue Thr172 by the upstream kinase liver kinase B1 (LKB1, also known as STK11), the protein product of the tumor suppressor gene mutated in the Peutz-Jeghers cancer predisposition syndrome." (PMID 21470407, 2011). "A few oncogenes (e.g. phosphatidylinositol 3-kinase, activated AKT1) inhibit autophagy, while numerous tumor suppressors (e.g. BH3-only proteins, death-associated protein kinase-1, PTEN, tuberous sclerosic complex 1 and 2, TSC1 and TSC2 and LKB1/STK11) induce autophagy." (PMID 21191146, 2010). "LKB1/STK11 functions as a tumour suppressor in hamartomous polyps and in neoplasms." (PMID 12865922, 2003). "Indeed, alterations in KEAP1 and/or STK11, which are especially frequent in KRAS-mutated tumours, promote an immunosuppressive tumour microenvironment, enriched in suppressive myeloid cells and depleted in CD8+ cytotoxic T cells, but with relative sparing of CD4+ effector T cells." (PMID 40849356, 2025).
tumor (continued). "Nutrient composition in the tumour microenvironment, metabolic alterations (e.g. anaplerosis), or other gene mutations (e.g. STK11) may therefore affect [18F]FSPG irrespective of NRF2 status." (PMID 39690148, 2024). "As a whole, it is not clear how STK11 mutations affect the tumor immune microenvironment." (PMID 38736875, 2024). "Histologically, SMARCA4-DTS is a poorly differentiated tumor with rhabdoid or epithelioid features that can be distinguished from other soft tissue, and thoracic sarcomas by a higher tumor mutation burden (TMB) and the presence of smoking signatures, including KRAS, STK11, and KEAP1 mutations." (PMID 37378131, 2023). "Furthermore, a lack of STK11 signaling triggers the accumulation of pro-tumoral immune cells caused by tumor expression of IL-6, CXCL7, CXCL5 or G-CSF, thus favoring the recruitment of neutrophils." (PMID 37370686, 2023). "Besides, by analyzing samples from LUAD patients with STK11 mutations, this study suggested that STK11 may affect LUAD progression by affecting the differentiation and infiltration of M1 macrophages in tumor tissue." (PMID 37506141, 2023). "Moreover, STK11 is associated with diminished immunotherapy response; and BRAF variants, which are associated with a higher tumor burden, may make tumors vulnerable to immunotherapy." (PMID 37152678, 2023). "Interestingly, the PD-L1 Tumor Proportion Score (TPS) tended to be lower in the patients with vs. without STK11 mutations (0% vs. 15%), and the TMB score tended to be higher in patients with STK11 mutations (209 vs. 146)." (PMID 37373999, 2023). "Moreover, STK11 mutations often coexist with KEAP1 mutations that relate to cellular resistance to oxidative stress, and co-occurrence of KEAP1 mutations and PTEN inactivation is an indicator of an immunologically “cold” tumor." (PMID 36131239, 2022). "Moreover, STK11/LKB1 has been reported to have tumor suppressor activity." (PMID 34831355, 2021). "No genetic alteration, including KRAS-mutant allele frequency or STK11 mutation status, was able to predict the anti-tumour activity, although baseline gene/protein expression of members of the HER family of receptor tyrosine kinase did exhibit a trend with the degree of anti-tumour response." (PMID 33466360, 2021). "Moreover, STK11 mutations are associated with a high disease aggressiveness in patients with KRAS exon 2 p.G12D mutation, while its loss of function has been linked to tumor development and progression." (PMID 34944952, 2021).